CPE (carboxypeptidase E)
Description:
Sorting receptor that directs prohormones to the regulated secretory pathway. Also acts as a prohormone processing enzyme in neuro/endocrine cells, removing dibasic residues from the C-terminal end of peptide hormone precursors after initial endoprotease cleavage.
Synonyms: CPH; BDVS; IDDHH
Tractability: Antibody: its Gene Ontology location is reachable by antibodies, with high confidence; UniProt places it where antibodies can reach, with medium confidence; UniProt predicts a signal peptide or a membrane-spanning region. PROTAC: ubiquitination databases record sites on it; its protein half-life has been measured.
Gene: Protein-coding gene on chromosome 4 (165,361,194 to 165,498,547, forward strand). Ensembl gene ENSG00000109472.
Subcellular location: Cytoplasmic vesicle, secretory vesicle (Isoform 1); Cytoplasmic vesicle, secretory vesicle membrane; Secreted
Subcellular location (Human Protein Atlas): Centrosome; Vesicles
Pathways (Reactome):
Metabolism of proteins: Insulin processing
Gene Ontology:
Molecular function: cell adhesion molecule binding; neurexin family protein binding; protein binding; carboxypeptidase activity; metallocarboxypeptidase activity; zinc ion binding
Biological process: cardiac left ventricle morphogenesis; protein localization to membrane; Wnt signaling pathway; neuropeptide signaling pathway; peptide metabolic process; protein modification process; protein processing; cell communication; intracellular protein localization; proteolysis; signaling
Cellular component: extracellular exosome; Golgi apparatus; extracellular region; plasma membrane; cytoplasm; endomembrane system; membrane; secretory granule; secretory granule membrane; transport vesicle; transport vesicle membrane
Genetic constraint (gnomAD): Loss-of-function variants: 13 observed, 36.57 expected, observed/expected ratio (o/e) 0.36, 90% interval 0.23 to 0.56. The upper end of that interval is the gene's LOEUF score, 0.56, which puts it in group 2 of 6, group 1 being the genes least tolerant of losing a copy. Missense variants: 453 observed, 517.15 expected, observed/expected ratio (o/e) 0.88, 90% interval 0.81 to 0.95. Synonymous variants: 204 observed, 198.47 expected, observed/expected ratio (o/e) 1.03, 90% interval 0.92 to 1.15.
Homologues: Orthologues: chimpanzee CPE (99% identical), macaque CPE (99% identical), mouse Cpe (97% identical), rat Cpe (96% identical), guinea pig CPE (96% identical), pig CPE (93% identical), dog CPE (79% identical), tropical clawed frog cpe (79% identical), zebrafish cpe (76% identical). Paralogues in human: CPN1 (47% identical), CPZ (46% identical), CPD (45% identical), CPXM1 (43% identical), CPXM2 (42% identical), AEBP1 (40% identical), CPM (37% identical).
Diseases named in the same sentence as CPE in open-access papers:
CPE is named in the same sentence as 87 diseases in open-access papers, as found by Europe PMC text mining. Sharing a sentence is not in itself a finding about the gene and the disease. The quoted sentences say what the papers report.
Obesity (17 papers, 2009 to 2025). Accumulation of substantial excess body fat. "A naturally occurring obesity phenotype mouse mutation, named “fat”, has been mapped to the CPE gene." (PMID 37100779, 2023). "A case report indicated that a homozygous nonsense mutation in the CPE gene is associated with clinical phenotypes composed of obesity, intellectual disability and hypogonadism." (PMID 37100779, 2023). "In this study, we present three affected siblings having the same homozygous c.405C>A (p.Y135*) mutation in CPE, which can be classified as a distinct syndromic obesity gene." (PMID 32936766, 2021). "Carboxypeptidase E (CPE), also known as obesity susceptibility protein or neurotrophic factor‐α1, is recognized for its function in processing prohormones, including proinsulin and pro‐opiomelanocortin polypeptide." (PMID 32995694, 2020). "The CPE gene has been strongly implicated in diabetes, with mutation in the human CPE gene identified as the likely cause of a genetic disease characterised by obesity, type 2 diabetes, intellectual disability and hypogonadotrophic hypogonadism." (PMID 32216834, 2020). "Food intake drives obesity in strains deficient for melanocortin 2 receptor accessory protein 2, Mrap2-/-, carboxypeptidase E, Cpe-/-, proprotein convertase 1, Pcsk1+/-, or growth differentiation factor 15, Gdf15-/-." (PMID 32356724, 2020). "CPE (carboxypeptidase E), an obesity susceptibility gene, has been shown to be responsible for the processing of pro-CCK into its bioactive forms." (PMID 32690984, 2020). "The carboxypeptidase E (CPE) is an obesity susceptibility gene encoding a prohormone processing enzyme (initially described by Fricker LD and HookVY in 1982)." (PMID 28114332, 2017). "Animal model studies have associated mutations in the CPE gene with obesity, diabetes, infertility, and hyperinsulinemia in mice." (PMID 26545240, 2015). "Among these, regression analysis found four well-established obesity associated genes that were positively correlated (CPE, LEP, NPY1R, and NPY5R), and two genes (APOM, and CRP) that were negatively correlated with weight gain." (PMID 23544116, 2013). "In humans, mutations in CPE have also been identified in patients with severe obesity." (PMID 40702736, 2025). "CPE knock-out mice and mice bearing a Ser202Pro mutation led to endocrine and neurological disorders including obesity, diabetes, neurodegeneration and infertility, while a human CPE truncating null mutation found in a patient, exhibited obesity, type 2 diabetes and intellectual disability." (PMID 28114332, 2017). "This is thought to be due to the severe disruption of the body weight-lowering peptides Therefore, the homozygous null mutation in the CPE gene is a plausible explanation for the proband’s hyperphagia and obesity, with multiple hormones/neuropeptides likely to be involved in the pathogenesis." (PMID 26120850, 2015). "Only one of these was within a candidate gene for obesity: a frameshift deletion, c.76_98del, in exon 1 of the CPE gene, resulting in a p.E26RfsX68 truncation of the protein." (PMID 26120850, 2015). "One group of genes (SERPINA12, CPE, SERPINA11, MTCH2, PNPLA5, INTS1, APOM) was associated (cosine value >0.1) with obesity and diabetes." (PMID 23544116, 2013). "Notably, while β-cell CPE deficiency does not result in spontaneous onset of obesity and hyperglycemia, it leads to accelerated development of streptozotocin-induced hyperglycemia in mice, pointing toward protective roles of CPE in the progression of T1D." (PMID 37967211, 2023). "Thus, CPE deficiency leads to development of obesity at an early age, which is not paralleled with development of low bone mass." (PMID 32995694, 2020). "Due to the lack of enzymatic activity, this mutation in the CPE gene could result in or contribute towards diseases such as diabetes, obesity and infertility as were observed in the CPE knock mouse and mice bearing the Ser202Pro mutation lacking CPE." (PMID 28114332, 2017).
Obesity (continued). "This cleavage is mediated by prohormone convertases such as PC1, PC2, CPE, and peptidyl α–amidating monooxygenase suggesting that inactivated PC1 and CPE play a role in obesity." (PMID 32936766, 2021). "Taken together, our results reveal a novel role for CPE in the regulation of DAT trafficking and DAT-mediated DA uptake, which may provide a novel target in the treatment of dopamine-governed diseases such as drug addiction and obesity." (PMID 19419578, 2009). "Furthermore, both CPE and the DAT may have roles in obesity and it will be interesting to investigate if this interaction contributes to the pathophysiology of this disease." (PMID 19419578, 2009).
Alzheimer disease (10 papers, 2016 to 2025). A progressive, neurodegenerative disease characterized by loss of function and death of nerve cells in several areas of the brain leading to loss of cognitive function such as memory and language. "A study on patients with Alzheimer’s disease suggested that a carboxypeptidase E/neurotrophic factor-α1 gene mutation in humans leads to impaired memory acquisition and depressive-like symptoms in transgenic mice." (PMID 39416947, 2024). "In fact, mutation in the CPE gene has been found in the brain from a patient with Alzheimer’ disease." (PMID 28114332, 2017). "However, it remains unknown whether these events occur in the hippocampus, and what the role of CPE is in the adult hippocampal neurogenesis in the context of Alzheimer’s disease (AD)." (PMID 38671492, 2024).
diabetes (8 papers, 2013 to 2024). "Carboxypeptidase E is a target of autoimmunity in late-onset (latent) autoimmune diabetes of adults with some diagnostic value to distinguish it from diabetes mellitus type 2." (PMID 36766627, 2023). "For example, carboxypeptidase E (CPE), known for its role in processing prohormones and proneuropeptides, has been identified as having a significant association with diabetes, hyperproinsulinemia, and reduced BMD." (PMID 39526243, 2024). "Our osteoclast eQTL data indicates that the human CPE gene has a role in bone density regulation and highlights this gene as a potential pleiotropic locus relevant to diabetes and osteoporosis." (PMID 32216834, 2020).
type 2 diabetes (8 papers, 2013 to 2023). "The SNP rs144727363 (C- to T-allele, Arg189Trp) in the CPE coding region changes arginine to tryptophan, which reduces enzymatic activity of CPE, and is associated with hyperproinsulinemia and type II diabetes mellitus in affected Ashkenazi Jewish families." (PMID 23964269, 2013). "The mutation alters CPE enzyme activity, and patients show early onset of type 2 diabetes." (PMID 37100779, 2023). "In addition, CPE missense polymorphism has been found in type 2 diabetes patients." (PMID 37100779, 2023). "A number of the genes highlighted in this study present strongly as having a potential role in bone biology, including CPE, FBN2, FLCN and RIPK3, and our results support the growing body of evidence suggesting that the CPE gene may exert pleiotropic effects on type 2 diabetes and osteoporosis." (PMID 32216834, 2020). "While islets of donors with type 2 diabetes do not display reduced expression of PC1/3 (also known as PCSK1) and/or CPE mRNA, one study found that palmitate treatment of islets isolated from non-diabetic deceased organ donors reduced CPE protein levels." (PMID 32894308, 2020).
pancreatic cancer (7 papers, 2019 to 2025). "For example, carboxypeptidase A1 (CPA1) has been found to be overexpressed in pancreatic cancer, while carboxypeptidase E (CPE) has been implicated in the progression of colorectal cancer." (PMID 39170262, 2024). "In pancreatic tumors, other CPs have been reported, such as the carboxypeptidase E promoting proliferation and regulating the transcriptional and epigenetic profiles." (PMID 37628784, 2023). "SCG5, CRYBA2, CPE and CHGB genes are associated with the prognosis of pancreatic cancer, and their low expression suggests a poor prognosis." (PMID 33164330, 2020). "In this study, we have investigated the role of wild-type Carboxypeptidase E (CPE-WT) and a 40 kDa N-terminal truncated isoform, CPE-ΔN in promoting proliferation and invasion of Panc-1 cells, a pancreatic cancer cell line." (PMID 31731578, 2019). "Prognostic analysis showed the expression levels of four genes were significantly correlated with the overall survival time of patients with pancreatic cancer, namely SCG5, CRYBA2, CPE and CHGB." (PMID 33164330, 2020). "Here, we investigated whether CPE-WT and 40 kDa CPE-ΔN isoform are expressed in Panc-1 and BXPC-3 pancreatic cancer cell lines." (PMID 31731578, 2019).
cervical cancer (5 papers, 2017 to 2024). A primary or metastatic malignant neoplasm involving the cervix. "CPE is a member of metallocarboxypeptidases family, and the CPE mRNA expression level can predict tumor recurrence in early-stage hepatocellular carcinoma, and predict poor prognosis in early-stage cervical cancer." (PMID 29158988, 2017). "Furthermore, we found that three of the signature genes (FNDC3A, VEGFA or CPE) function as oncogenes to promote the proliferation, invasion and migration of cervical cancer cells and could be potential therapeutic targets for CC." (PMID 34630524, 2021). "Aberrant expression of CPE has been found in several major tumors of epithelial origin, including lung, liver, colon, pancreatic and cervical cancers, as well as in neuroendocrine tumors such as insulinoma, suggesting CPE might have a role in tumor progression." (PMID 31798768, 2019). "Among the multiple proteins secreted by cervical cancer cells, four upregulated proteins were identified: nucleobindin-1 (NUCB1), carboxypeptidase E (CPE), calreticulin (CALR), and heat-shock protein beta-1 (HSPB1)." (PMID 36992411, 2023).
hepatocellular carcinoma (5 papers, 2017 to 2025). A malignant tumor that arises from hepatocytes. "A CPE mRNA splice variant encoding a 40 kDa CPE-ΔN isoform has recently been cloned from hepatocellular carcinoma (HCC) cells and shown to be 1.7 kb in size." (PMID 31731578, 2019). "Previous work on carboxypeptidase E (CPE) demonstrated that association with EVs was required for CPE to induce proliferation and growth of hepatocellular carcinoma cells." (PMID 41400998, 2025). "Carboxypeptidase E (CPE) supports the progression of different cancers, including hepatocellular carcinoma (HCC)." (PMID 35328535, 2022). "Clinical studies have demonstrated that elevated CPE mRNA and protein levels are correlated with poor prognosis in colorectal, hepatocellular carcinoma, and cervical cancer patients." (PMID 31731578, 2019).
Intellectual disability (5 papers, 2016 to 2023). "Only one patient is described with morbid obesity, intellectual disability, abnormal glucose homeostasis and hypogonadotropic hypogonadism, which was associated with a homozygous frameshift deletion in CPE." (PMID 32936766, 2021). "Furthermore, a person who bears homozygosity for a truncating mutation of the CPE gene displayed intellectual disability." (PMID 28114332, 2017). "Indeed, a recent study showed that a truncating mutation of the CPE gene found in a female from a consanguineous family, led to morbid obesity, intellectual disability, hypogonadotrophic hypogonadism and abnormal glucose homeostasis." (PMID 28114332, 2017). "In addition, the recent description of the first human with a truncating homozygous null mutation for CPE presenting with intellectual disability, further supports the importance of the CPE protein in cognitive function in humans." (PMID 27922637, 2016).
breast cancer (4 papers, 2015 to 2022). A primary or metastatic malignant neoplasm involving the breast. "A splicing variant of CPE (carboxypeptidase-E) stimulates growth, and it is a biomarker for mammary tumor metastatic spread." (PMID 25888236, 2015).
cognitive decline (4 papers, 2021 to 2025). "Our previous studies have shown that hippocampal delivery of AAV-NF-α1/CPE (mouse) in 3 × Tg-AD mouse model prevented cognitive decline, neurodegeneration, and amyloid and tau pathology." (PMID 41291954, 2025). "Recent work from several laboratories have demonstrated that delivery of AAV- or lentivirus-NF-α1/CPE or upregulation of NF-α1/CPE expression by agomirs can rescue AD pathology and ameliorate cognitive decline in three different AD mouse models." (PMID 41291954, 2025). "3xTg-AD and non-Tg mice received bilateral hippocampal injections of either AAV-GFP, NF-α1/CPE, or NF-α1/CPE-E342Q at age 2 months (presymptomatic) and they then underwent a series of behavioral tests at age 9 months when cognitive decline was evident." (PMID 40568106, 2025). "Our previous studies have shown that hippocampal delivery of AAV- NF-α1/CPE (mouse) in 3xTg -AD mouse model prevented cognitive decline, neurodegeneration, and amyloid and tau pathology." (PMID 40568106, 2025). "We then generated knock-in mice, replacing WT-CPE with enzymatically inactive CPE-E342Q, and determined if these mice were protected from stress-induced CA3 degeneration and cognitive decline." (PMID 33414376, 2021).
glioma (4 papers, 2012 to 2025). A benign or malignant brain and spinal cord tumor that arises from glial cells (astrocytes, oligodendrocytes, ependymal cells). "Similar to miRNA-451, another study found that carboxypeptidase E (CPE), a secreted neuropeptide-processing enzyme, also possesses an anti-migratory and pro-proliferative capacity, modulating the growth behavior of glioma cells in response to hypoxia and glucose deprivation." (PMID 28821904, 2018). "Additionally, carboxypeptidase E (CPE), a neuropeptide-processing enzyme, has a pro-proliferative and anti-migratory role in glioma cells." (PMID 23185366, 2012).
Infertility (4 papers, 2015 to 2021). "Breeding of heterozygote with homozygote, or homozygote with homozygote, males or females, failed to produce any pregnancies, indicating infertility, similar to CPE-KO mice." (PMID 33414376, 2021).
osteosarcoma (4 papers, 2019 to 2023). A usually aggressive malignant bone-forming mesenchymal neoplasm, predominantly affecting adolescents and young adults. "CPE is a prohormone processing enzyme that is usually overexpressed in osteosarcoma cell lines, and the downregulation of CPE inhibits the migration and invasive ability of osteosarcoma cells." (PMID 37937197, 2023).
type 1 diabetes (4 papers, 2018 to 2023). "In the case of type 1 diabetes (T1D), dysregulation of prohormone processing, including the carboxypeptidase E (CPE) pathway, has been extensively reported." (PMID 37967211, 2023). "Finally, the CPE gene was suggested to influence Type I diabetes mellitus whereas GRID2 and PTGDR are responsible for neuroactive ligand-receptor interaction." (PMID 36011330, 2022). "Our data are also consistent with other evidence implying that the prohormone convertases and carboxypeptidase E involved in proinsulin cleavage may become downregulated in type 1 diabetes." (PMID 32172310, 2020).
cognitive deficits (3 papers, 2023 to 2025). "Research indicates that viral delivery of Neurotrophic Factor‐α1/Carboxypeptidase E (NF‐α1/CPE) in the hippocampus prevented the later development of cognitive deficits in mice, supporting the promise of gene therapy for AD." (PMID 41363055, 2025). "Thus NF-α1/CPE gene therapy targets many regulatory components to prevent cognitive deficits in 3xTg-AD mice and has implications as a new therapy to prevent AD progression by promoting cell survival, inhibiting APP overexpression and tau hyperphosphorylation." (PMID 37369719, 2023).